GZMB (granzyme B)
Diseases named in the same sentence as GZMB in open-access papers (continued):
Sharing a sentence is not in itself a finding about the gene and the disease.
infection (continued). "However, inhibition of PI3Kδ does not prevent the differentiation of naive CD8+ T cells into competent long-lived CD8+ Tmem, nor for Teff to produce IFN-γ and GzmB in response to infection in vivo." (PMID 26311905, 2015). "From 15 days post-infection onwards, T cell responses in the LNs decreased and we could not detect any CD4+ Granzyme B+ T cell subset, showing that the induction of Granzyme B-expressing CD4+ T cells correlates with the triggering of CD4+ and CD8+ T cell responses." (PMID 24367519, 2013). "However, we did not observe reduced production of granzyme B. Similarly, Hickman and colleagues, showed that specific CD8+ T cells from CXCR3-deficient mice had reduced cytotoxicity when compared to control group during the infection with vaccinia virus model." (PMID 32574175, 2020). "Although the correlation with Perf/GzmB expression may be prone to underestimation because of the prior release of cytotoxic molecules in vivo during ongoing infection, ∼5% of Perf/GzmB+ pMHCII tetramer+ CD4+ T cells lacked expression of Eomes, Hobit, and CX3CR1." (PMID 31308093, 2019). "Moreover, the granzyme b, nk-lysin, ifnγ, il4 and il10 mRNA levels in early skin-draining lymph nodes of immunized pigs were higher than those in pigs with non-irradiated cercariae infection." (PMID 20976218, 2010). "There was no significant alterations in production of TNF, granzyme B (GZMB), or perforin between adult or aged animals irrespective of infection status." (PMID 39550693, 2025). "Flow cytometric analysis revealed no statistical difference in the frequency of granzyme B and C expressing CD8+ TRM in the skin during secondary infection in the presence or absence of cognate Ag." (PMID 37809077, 2023). "After viral challenge, we found higher frequencies of Granzyme B expressing DP T cells compared to CD4 T cells and, most notably, CD8 T cells at each timepoint post infection." (PMID 34929014, 2021). "Granzyme B expressing MAIT and non-MAIT cells fluctuated over the course of vaccination, however, after infection, more CD8+ non-MAIT cells expressed Granzyme B compared to MAIT cells." (PMID 32572140, 2020). "CD107a expression was similar in CD4 and CD8 T cells, unlike perforin and granzyme B. CD107a slightly increased in expression in CD4 and CD8 T cells over the course of infection." (PMID 27760221, 2016). "The proportion of cells expressing granzyme B and/or perforin within either CD38+ or CD38- CD4+ T cell subsets did not change markedly during the course of infection." (PMID 27662621, 2016). "We found higher GZMB expression by natural killer (NK) cells (CD8(+)CD3(-)), but not by T cells (CD8(+)CD3(+)), in G1(+) macaques prior to infection (P = 0.0163) and at the peak of virus replication on day 14 post-challenge (P = 0.0167)." (PMID 25418588, 2014). "At 6 d post-infection splenic CD8+ cells were enriched and found to express gzmA, gzmB and gzmK mRNA but not gzmC in wt animals." (PMID 19838298, 2009). "However, this modulation only minimally altered Tcf-1+ and GzmB+ subsets, nor did it enhance CXCR5 expression within the Tcf-1+ subset, contrasting the patterns observed in s.c. infection routes." (PMID 40169810, 2025). "FTY720 treatment did not affect GzmB levels in BAL fluid nor Ifng mRNA expression in the lungs, implying that lung resident cells are primarily responsible for the production of these mediators at day 4 post re-infection." (PMID 35108347, 2022). "Following challenge with wild-type L. major, TRM cells specific to L. major were rapidly recruited and proliferated at the site of infection in the immunized mice and induced higher levels of IFN-γ and Granzyme B in the immunized and leishmanized mice than non-immunized mice." (PMID 35419001, 2022).
infection (continued). "Decidua from 10 ZIKV-infected dams obtained 16-56 days post infection at third (n=9) or second (n=1) trimester showed a significant reduction in frequency of activated, CXCR3+, and/or Granzyme B+ memory CD4+ and CD8+ T lymphocytes and γδ T compared to normal decidua." (PMID 34394129, 2021). "The hepatic NK cells population and IFN-γproduction were decreased respectively at 2, 4, 12 weeks post E. multilocularis inoculation, but at 24th week after infection no change was observed, while TNF-α and granzyme B levels had no significance in designated time points." (PMID 31500589, 2019). "Adult and aged CD8+ T cells also displayed increased expression of GZMB following MHV‐A59 infection, albeit not to statistically significant levels; therefore, it is likely that IFN‐γ may act in concert with other inflammatory mediators to contribute to neuronal death in our infection model." (PMID 39550693, 2025).
bacterial infection (9 papers, 2011 to 2025). "In our model of extracellular bacterial infection in vivo, we have shown that memory NK cells lead to more Granzyme B production in the lungs of protected mice, suggesting this effector protein could contribute to host protection against S. pneumoniae." (PMID 37486946, 2023). "Moreover, CTRP9 knockdown reduced the frequency of Granzyme B-producing T cells, impaired the transcriptional upregulation of Perforin A, Granzyme B, TNF-α, and IL-6, ultimately resulting in increased susceptibility to bacterial infection and elevated mortality." (PMID 41249580, 2025). "The cytolytic granules have been shown to contain chemokines such as CCL3, CCL4 and CCL5 in addition to the classical mediators of cytotoxicity (GZMB, PRF1 and GNLY), in both viral and bacterial infections, indicating their role in cytolysis." (PMID 38501302, 2024). "Administration of the AdipoR1 antibody during bacterial infection impaired the inducible expression of cytotoxic genes Perforin A and Granzyme B and pro-inflammatory cytokines IFN-γ, TNF-α, and IL-6 and reduced the ability of T cells to produce Granzyme B." (PMID 41249580, 2025). "In our experimental model, TNF-α secretion was essentially driven by the bacterial infection and was not further enhanced by GzmB treatment." (PMID 32151975, 2020). "We postulate that the increased cellular infiltration was part of the host immune response to control the intracellular bacterial infection; however, this immune response, including upregulated IFN-γ and granzyme B, remained ineffective in CD8-/- and MHC I-/- mice." (PMID 28723951, 2017). "Notably, the loss of CaMKKβ activity inhibited the ability of tilapia leukocytes to express Perforin A, Granzyme B, IFN-γ, TNF-α, and IL-6 and reduced the frequency of Granzyme B-producing T cells, consequently impairing the ability to control bacterial infection." (PMID 41249580, 2025). "Interestingly, we demonstrate that NK cell protection is mediated through higher levels of cytotoxic products (Granzyme B and Perforin), and not through IFNγ mediated responses or inflammatory cell recruitment, thereby revealing a novel role for NK cells in bacterial infection." (PMID 37486946, 2023).
cardiovascular disease (9 papers, 2010 to 2023). "The gene GZMB encodes the granzyme B, secreted by natural killer cells and cytotoxic T-lymphocytes to induce inflammatory reactions by processing cytokines and imparting into chronic inflammations, including RA and cardiovascular diseases." (PMID 36072953, 2022).
immune dysfunctions (5 papers, 2017 to 2022). "Granzyme B-expressing (GrB+) B cells are thought to contribute to immune dysfunctions in HIV patients, but so far their exact role is unknown." (PMID 27779180, 2017).
hematological malignancies (4 papers, 2011 to 2024). "Conversely, cytotoxic DN T-cells generate IFN-γ, perforin, and granzyme B, thereby having a cytotoxic effect on hematologic malignancies and solid tumors." (PMID 39544989, 2024). "The granzyme B genotypes were retrospectively analyzed in a cohort of 613 pairs of recipients with hematological malignancies and their unrelated donors." (PMID 21886827, 2011). "In hematological malignancies, BTLA/HVEM axis dysregulation decreased perforin and granzyme B production by BTLA+ T cells and was associated with poor outcome in DLBCL and FL, whereas only two studies reported about BTLA and HVEM expression on leukemic cells from CLL." (PMID 33917094, 2021).
metabolic disease (4 papers, 2020 to 2025). A congenital disorder (due to inherited enzyme abnormality) or acquired (due to failure of a metabolically important organ) disorder resulting from an abnormal metabolic process. "Nonetheless, the upregulation of Fas on T-cells is compatible with low levels of perforin, granzyme B, and interferon γ secretion and elevated levels of complement and caspase proteins in various metabolic disorders." (PMID 33808960, 2021).
adenocarcinoma (3 papers, 2021 to 2023). A common cancer characterized by the presence of malignant glandular cells. "Histological scores for MCPT1+, MCPT6+ and granzyme B+ ieMMCs showed that ieMMC density decreased from precursor lesions (atypical hyperplasia; LG; HG adenoma) to adenocarcinoma (p < 0.001)." (PMID 35565377, 2022).
infectious disease (3 papers, 2017 to 2025). A disorder directly resulting from the presence and activity of a microbial, viral, or parasitic agent in humans. "Recently, the induction of B cell-derived granzyme B (GrB) has been described in the context of infectious diseases." (PMID 32886698, 2020).
inflammation (3 papers, 2018 to 2025). Aberrant reaction of the microcirculation characterized by movement of fluid and leukocytes from the blood into extravascular tissues. "However, a study of mice experimentally infected with Klebsiella pneumoniae found that while GZMB knockout mice had higher levels of lung inflammation at earlier stages in the disease, there were minimal differences in distant organ injury or survival between the knockout and wild type mice." (PMID 31611566, 2019).
respiratory diseases (3 papers, 2023 to 2026). "The simultaneous GzmB and PRF‐targeting EG‐FET‐type biosensor is developed for the diagnosis of respiratory diseases." (PMID 41550856, 2026).
blood cancer (2 papers, 2016 to 2021). "However, the integrity of GzmB function in CD4+ T cells may need to be maintained in order to optimize the GVT effect for certain types of blood cancers that are sensitive to GzmB-mediated killing by CD4+ T cells." (PMID 27774524, 2016).
kidney (2 papers, 2015 to 2021). "The urine and peripheral blood transcript levels of PRF1 and GZMB were shown to be increased in kidney transplant recipients with acute rejection." (PMID 26286066, 2015).
neurodegenerative disease (2 papers, 2015 to 2023). A disorder of the central nervous system characterized by gradual and progressive loss of neural tissue and neurologic function. "In addition, Eomes+ Th cells are also observed to accumulate in the CNS during neurodegenerative diseases in mouse models and secreted granzyme B following stimulation by putative CNS antigens." (PMID 36980209, 2023).
neurological diseases (2 papers, 2022 to 2024). "Furthermore, a few studies have implicated GzmB in T cell-mediated neurological disorders." (PMID 38846935, 2024).
vasculopathy (2 papers, 2020 to 2025). "When Serp-2 is given to mice after implant of granzyme B-deficient aortic transplants, the efficacy for reducing graft vasculopathy is lost, indicating that Serp-2 immune-modulating functions in this transplant model are at least in part dependent upon blockade of granzyme B and apoptosis." (PMID 32244484, 2020).
kidney diseases (1 paper, 2025). "Previous studies on GZMB in kidney diseases primarily emphasized its elevated expression in CD8+ T cells." (PMID 41244830, 2025). "It is well known that podocytes and mesangial cells are two specialized cell types in the glomerulus that play critical roles in kidney diseases, yet their relationship with GZMB remains unclear." (PMID 41244830, 2025).
GZMB also shares sentences with these, for which no sentence is quoted: Insulin resistance (6 papers); type 2 diabetes (6); inflammatory bowel disease (5); age-related macular degeneration (4); bronchiectasis (3); heart disease (3); idiopathic pulmonary fibrosis (3); juvenile idiopathic arthritis (3); keloid (3); multiple myeloma (3); respiratory syncytial virus infection (3); septic shock (3); unstable angina (3); abdominal aortic aneurysm (2); acute coronary syndrome (2); acute lymphoblastic leukemia (2); alopecia areata (2); Berardinelli-Seip congenital lipodystrophy (2); bone cyst (2); coronary artery disease (2); cyst (2); cystic fibrosis (2); gastric tumors (2); Hyperinsulinemia (2); Hypertension (2); hypertriglyceridemia (2); kidney transplant (2); laryngeal carcinoma (2); Listeria infection (2); Lung Squamous Cell Carcinoma (2).
A further 123 diseases each share a sentence with GZMB in 2 papers or fewer.